MSI2 (musashi RNA binding protein 2)
Description:
RNA binding protein that regulates the expression of target mRNAs at the translation level. May play a role in the proliferation and maintenance of stem cells in the central nervous system (By similarity).
Synonyms: MSI2H
Tractability: PROTAC: UniProt records ubiquitination sites on it; ubiquitination databases record sites on it; its protein half-life has been measured.
Gene: Protein-coding gene on chromosome 17 (57,255,851 to 57,684,689, forward strand). Ensembl gene ENSG00000153944.
Subcellular location: Cytoplasm
Subcellular location (Human Protein Atlas): Cytosol
Pathways (Reactome):
Signal Transduction: RHOBTB2 GTPase cycle
Gene Ontology:
Molecular function: identical protein binding; protein binding; RNA binding; nucleic acid binding; poly(U) RNA binding; single-stranded RNA binding
Biological process: central nervous system development; regulation of translation; stem cell development
Cellular component: cytosol; cytoplasm
Genetic constraint (gnomAD): Loss-of-function variants: 13 observed, 31.96 expected, observed/expected ratio (o/e) 0.41, 90% interval 0.26 to 0.65. The upper end of that interval is the gene's LOEUF score, 0.65, which puts it in group 2 of 6, group 1 being the genes least tolerant of losing a copy. Missense variants: 237 observed, 359.76 expected, observed/expected ratio (o/e) 0.66, 90% interval 0.59 to 0.73. Synonymous variants: 131 observed, 134.26 expected, observed/expected ratio (o/e) 0.98, 90% interval 0.85 to 1.13.
Homologues: Orthologues: mouse Msi2 (99% identical), rat Msi2 (99% identical), tropical clawed frog msi2 (97% identical), pig MSI2 (96% identical), zebrafish msi2b (95% identical), chimpanzee MSI2 (93% identical), rabbit MSI2 (93% identical), zebrafish msi2a (93% identical), macaque MSI2 (84% identical), guinea pig MSI2 (84% identical), dog MSI2 (79% identical), Drosophila melanogaster Rbp6 (57% identical), and 2 more. Paralogues in human: MSI1 (77% identical), DAZAP1 (39% identical), HNRNPA3 (36% identical), HNRNPDL (35% identical), HNRNPAB (34% identical), HNRNPD (34% identical), HNRNPA1 (33% identical), HNRNPA1L3 (32% identical), HNRNPA1L2 (32% identical), HNRNPA0 (31% identical), HNRNPA2B1 (31% identical), RBMX (28% identical), and 24 more.
Diseases named in the same sentence as MSI2 in open-access papers:
MSI2 is named in the same sentence as 116 diseases in open-access papers, as found by Europe PMC text mining. Sharing a sentence is not in itself a finding about the gene and the disease. The quoted sentences say what the papers report.
leukemia (41 papers, 2012 to 2026). A malignant (clonal) hematologic disorder, involving hematopoietic stem cells and characterized by the presence of primitive or atypical myeloid or lymphoid cells in the bone marrow and the blood. "Musashi-2 (MSI2), a stem cell-associated RNA-binding protein, is highly expressed in leukemia and is correlated with enhanced proliferation and reduced apoptosis; its downregulation leads to increased apoptosis and growth inhibition." (PMID 41234470, 2025). "Utilizing an MLL-AF9 AML Msi2 conditional knockout model, Michael Kharas’ group determined that Msi2 deficiency led to a significant delay in leukemia development, decrease in leukemic cell infiltration, and a significant decrease in LICs (CD11b + Kit +)." (PMID 36307883, 2022). "Remarkably, excessive MSI2 expression associates with tumorigenesis and poor prognosis in multiple cancers as well as in different types of leukemias." (PMID 33504942, 2021). "For instance, both Msi1 and Msi2 have been implicated in colon cancer, but Msi1 and Msi2 have unique ties to glioblastoma and leukemia, respectively." (PMID 35011618, 2021). "A final refinement based on an extensive literature search to identify novel TFs, or those implicated in the regulation of stem cell function and/or leukemia, yielded a list of ten candidate regulators of primitive hematopoietic cell expression of MSI2." (PMID 29641991, 2018). "Msi2 has also been shown to be elevated in several leukemias and its elevated expression has been linked with poorer prognosis in these cancers." (PMID 22496868, 2012). "In addition, overexpressed MSI2 plays an oncogenic role in myeloid leukemia, with elevated expression of MSI2 is linked with poor survival in leukemia patients." (PMID 34237057, 2021). "ASOs targeting eIF4E, LIN28B, and Musashi-2 (MSI2) have shown robust anti-tumor activity in preclinical cancer models, particularly in leukemia and aggressive solid tumors, although challenges related to delivery, stability, and tissue specificity remain." (PMID 41596407, 2026). "Numb is suppressed by this rise in MSI2, which prevents differentiation and promotes the growth of undifferentiated leukemia stem cells (LSCs)." (PMID 41221040, 2025). "This oncogene strengthens the stem-like characteristics of leukemia cells and accelerates the course of the disease by indirectly suppressing Numb by raising MSI2 levels." (PMID 41221040, 2025). "Although both Msi1 and Msi2 are expressed in brain and testis, Msi2 is dominant in the hematopoietic tissues and functionally essential for normal hematopoietic stem cells and leukemia stem cells in myeloid leukemia." (PMID 38373797, 2024). "The ONCOMINE analysis indicated significant upregulation of MSI2 in lung cancer compared to adjacent normal tissues, as well as in breast cancer, colon cancer, gastric cancer, and leukemia." (PMID 38645664, 2024). "HEL cells invaded and infiltrated into BM and spleen tissues, which further proved that MSI2 promoted the leukemia progression in vivo." (PMID 37149661, 2023). "In the AML xenograft mouse model, overexpression of MSI2 recapitulated its leukemia-promoting effects, and overexpression of miR-143 partially attenuated tumor growth and prevented metastasis." (PMID 37149661, 2023). "HEL cells developed hindlimb paralysis earlier and more nodules in the liver, indicating that MSI2 overexpression boosts more leukemia cells to infiltrate into other organs and tissues." (PMID 37149661, 2023). "Musashi2 (MSI2) is a member of RNA‐binding proteins (RBPs), which plays prominent roles as an oncoprotein in various types of tumours, including leukemia, glioblastomas, pancreatic, breast, lung and colorectal cancers." (PMID 35073459, 2022). "MSI2 drives leukemia progression and stem cell renewal through a variety of mechanisms involving multiple pathways." (PMID 36167829, 2022). "HoxA9, c-Myc and Ikzf2 were shown to be targets of MSI2, maintaining the oncogenic leukemia stem cell (LSC) self-renewal program in AML." (PMID 36076951, 2022).
leukemia (continued). "We previously found that MSI2 maintains MLL-leukemia self-renewal programs by retaining the translation of HOXA9, c-MYC, MYB, and IKZF218,31." (PMID 36167829, 2022). "The screen we performed to identify differentially expressed surface proteins on Msi2+ leukemia cells led to the identification of Sdc1 as a key regulator of bcCML growth and propagation." (PMID 33243988, 2020). "Here, we show that a knock-in reporter mouse for the stem cell gene Musashi 2 (Msi2) allows identification of leukemia stem cells in aggressive myeloid malignancies, and provides a strategy for defining their core dependencies." (PMID 33243988, 2020). "Here the authors identify a small molecule inhibitor of MSI2 and characterize its effects in a murine leukemia model." (PMID 31217428, 2019). "Similar to Numb inducing, Msi2 inhibition can also induce differentiation in leukemia cells and inhibit the ability of proliferation and distribution." (PMID 31231484, 2019). "Using in vivo CML models in chronic phase and blast crisis suggested that Msi2-Numb can be a novel target for leukemia treatment since it can control CML stem cells differentiation and apoptosis." (PMID 31231484, 2019). "The relevance and requirement for MSI2’s function in leukemia was demonstrated by a series of depletion and overexpression studies in both mouse and human systems." (PMID 31217428, 2019). "Recently, Msi1 and Msi2 were found to be overexpressed in tumors of various organs and in leukemias." (PMID 28753936, 2017). "MSI2 overexpression can act as a cooperating oncogene and drive transformation, accelerate leukaemia and increase disease burden in the context of a MDS mouse model." (PMID 26898884, 2016). "Msi2 was also identified as part of a gene signature characterized by persistent Vp16-Meis transactivation in Hox models of leukemia." (PMID 26986211, 2016). "We observed a delay in the myeloid leukaemia (312 days compared with 96 days) in the control, and these leukaemias relapsed with MSI2 positivity, providing evidence that MSI2 overexpression must be sustained to maintain disease." (PMID 26898884, 2016). "Currently, relatively little is known about the roles of MSI2, but in mouse model of leukemia it is believed to down-regulate the protein Numb, which has been shown to regulate both Notch and Wnt signaling." (PMID 23667531, 2013). "Recent studies suggest that the translation of NUMB mRNA, which is a known target of MSI1, inversely correlates with MSI2 expression in leukemia." (PMID 23667531, 2013). "Techniques that block MSI2 or restore Numb expression may encourage leukemia cell differentiation, decrease the number of leukemia stem cells, and increase the efficacy of currently used therapies such tyrosine kinase inhibitors." (PMID 41221040, 2025). "While both MSI1 and MSI2 are found in the brain and testes, MSI2 predominates in hematopoietic tissues and plays a critical role in maintaining the normal function of hematopoietic stem cells and leukemia stem cells in myeloid leukemia." (PMID 38645664, 2024). "In contrast with MSI1, MSI2 expression has been predominantly reported in hematological neoplasms, fundamentally in leukemia, probably due to the fact that MSI2 is mainly expressed in the hematopoietic system and is an important regulator of hematopoietic stem cells (HSCs)." (PMID 36076951, 2022). "Besides the Ro-mediated inhibition of MSI2, other small molecule drugs targeting RBPs with potential use for leukemia treatment emerge." (PMID 32408494, 2020). "In addition, over 60% of MSI2 targets identified by HyperTRIBE in human leukemia cells are conserved in murine leukemia." (PMID 32332729, 2020). "The fact that Msi2+ leukemia cells had a greater capacity to propagate disease and were preferentially able to evade therapy suggested that the reporter might serve as a particularly important tool to identify regulators of these cells." (PMID 33243988, 2020).
leukemia (continued). "Besides its effects on leukemia progression, an enhanced chemosensitivity to daunorubicin has been demonstrated upon MSI2 silencing." (PMID 32408494, 2020). "Meanwhile, the small-molecule targeting of MSI2 activity is used in murine AML leukemia model." (PMID 31952541, 2020). "Besides inducing the Numb expression, the results showed that Msi2 gene inhibition by shRNA1 would significantly decrease in vivo leukemia growth and retention rate, especially in blast phase." (PMID 31231484, 2019). "Taken together, these studies suggest that the precise molecular regulation of MSI2 gene expression may be among the critical mechanisms underlying balanced HSC self-renewal/differentiation and the restraint of leukemia progression." (PMID 29641991, 2018). "Additionally, increased expression of Msi1 and Msi2 has been found in leukemias such as acute myelogenous leukemia and acute lymphoblastic leukemia." (PMID 28753936, 2017). "In myeloid leukemia, high Numb expression or MSI2 silence could make leukemia more differentiated and unable to propagate disease markedly." (PMID 27092875, 2017). "Furthermore, MSI2-overexpressing leukemia cells demonstrated reduced activity at these doses." (PMID 31217428, 2019). "MSI2 is also highly upregulated during human CML progression, and its expression serves as an early indicator of poor prognosis not only in leukemias but also in solid cancers like lung cancer." (PMID 38234720, 2023). "The motifs in 3’UTR are among consensus binding sites for RBP MSI2, which we previously found to cooperatively work with SYNCRIP to drive translation of shared target genes in leukemia cells." (PMID 37085479, 2023). "The Musashi family of RBPs, including MSI1 and MSI2, have been shown to play critical roles in MLL-r leukemia." (PMID 36307883, 2022). "Similar to MSI2, SYNCRIP was required for leukemia progression by utilizing an MLL-AF9 AML Syncrip knockout mouse model." (PMID 36307883, 2022). "In CLL, although high MSI2 levels can correlate with poor outcome, there are no studies addressing the function of MSI2 in CLL, how this affects leukemia-cell survival and growth and how this influences clinical outcome in patients or animal models." (PMID 33504942, 2021). "Moreover, we found that the enhanced RNA binding activity of MSI2 leads to differential regulation, e.g., at Hoxa9, Ikzf2, and Myb targets, in LSCs versus LSKs, which provides a possible explanation for the differential requirement of MSI2 in leukemia compared with normal hematopoiesis." (PMID 32332729, 2020). "Our results reveal that MSI2 not only enhances its RNA binding activity in LSCs versus LSKs overall, but also interacts more with genes regulated by the MLL leukemia programs in LSCs." (PMID 32332729, 2020). "We found that the GE independent shared targets, the majority of which have higher binding to MSI2 in LSCs versus LSKs, are enriched for both normal HSPC-related as well as MLL-AF9 leukemia programs." (PMID 32332729, 2020). "Remarkably, MSI2 controlled pathways in LSCs and MLL1-HOXA9-MEIS1 leukemia programs were selectively enriched in GE independent LSC unique targets, which are expressed at the same or lower level in LSKs." (PMID 32332729, 2020). "Top LSK-specific signatures include normal embryonic stem cell related programs, hematopoietic stem cells and progenitors programs, while MSI2 controlled pathways and MLL-AF9 AML leukemia are amongst the most enriched signatures in LSC-specific targets." (PMID 32332729, 2020). "Musashi RNA-binding protein 2 (MSI-2) was proposed to be a potential oncoprotein regulating cancer initiation, progression and drug resistance in leukemia and several solid tumors." (PMID 29073938, 2017). "Notably, several essential genes involved in HSC self-renewal, metabolism, and leukemia development were increased, including GATA2, MSI2, MYCN, CD44, GAS2, HOXB4, and HOXB6." (PMID 38216972, 2024).
leukemia (continued). "Regardless of the exact mechanism, our data support a leukemia-specific role for MSI2 and provide further rationale for targeting MSI2 in leukemia cells in patients that have equivalent expression of MSI2 as compared with normal cells." (PMID 32332729, 2020). "Utilizing a related compound with high affinity binding to NGF, we found that it no longer bound MSI2 and poorly inhibited leukemia cell growth." (PMID 31217428, 2019). "Our lab previously found that MSI2 directly binds to the mRNA of mixed-lineage leukaemia target genes including Hoxa9, Myc and Ikzf2, and regulates the translation of these targets in a mixed-lineage leukaemia-AF9 leukaemia model." (PMID 26898884, 2016). "To further examine if transient withdrawal of MSI2 expression could also delay the leukaemia, we transplanted NHD13/MSI2 cells and waited 2 weeks to induce MSI2 expression." (PMID 26898884, 2016). "LSCs have a self-renewal capacity to generate large numbers of leukemia progenitor cells (CD34+CD38+) through the activation of several signaling pathways including WNT/β-catenin, Hedgehog (Hh), Notch, transforming growth factor-β (TGF-β)/Forkhead box O (FOXO), and Musashi 2 (Msi2)-Numb signaling." (PMID 34922630, 2021). "MSI2, which is expressed predominantly in hematopoietic stem and progenitor cells (HSPCs), enforces HSPC expansion when overexpressed and is upregulated in myeloid leukemias, indicating its regulated transcription is critical to balanced self-renewal and leukemia restraint." (PMID 29641991, 2018). "While none of the mice transplanted with GFP− cells developed leukemia, all of the mice transplanted with GFP+ cells succumbed to bcCML, suggesting that the majority of LSC activity in vivo resides within the Msi2-expressing GFP+ fraction of the population." (PMID 33243988, 2020).